MEN1 (menin 1)
Description:
Essential component of a MLL/SET1 histone methyltransferase (HMT) complex, a complex that specifically methylates 'Lys-4' of histone H3 (H3K4). Functions as a transcriptional regulator. Binds to the TERT promoter and represses telomerase expression. Plays a role in TGFB1-mediated inhibition of cell-proliferation, possibly regulating SMAD3 transcriptional activity. Represses JUND-mediated transcriptional activation on AP1 sites, as well as that mediated by NFKB subunit RELA. Positively regulates HOXC8 and HOXC6 gene expression. May be involved in normal hematopoiesis through the activation of HOXA9 expression (By similarity). May be involved in DNA repair.
Synonyms: SCG2; MEAI
Tractability: Small molecule: a drug acting on it is in phase 1 trials; a structure with a bound ligand is known; a high-quality ligand is known. PROTAC: ubiquitination databases record sites on it; its protein half-life has been measured; a small molecule that binds it is known.
Chemical probes: M-808, MI-2
Gene: Protein-coding gene on chromosome 11 (64,803,510 to 64,811,294, reverse strand). Ensembl gene ENSG00000133895.
Subcellular location: Nucleus
Subcellular location (Human Protein Atlas): Nucleoplasm; Cytosol
Pathways (Reactome):
Signal Transduction: Deactivation of the beta-catenin transactivating complex; Formation of the beta-catenin:TCF transactivating complex; RHO GTPases activate IQGAPs; SMAD2/SMAD3:SMAD4 heterotrimer regulates transcription
Metabolism of proteins: Post-translational protein phosphorylation; Regulation of Insulin-like Growth Factor (IGF) transport and uptake by Insulin-like Growth Factor Binding Proteins (IGFBPs)
Developmental Biology: Differentiation of naive CD4+ T cells to T helper 2 cells (Th2 cells)
Gene expression (Transcription): Formation of WDR5-containing histone-modifying complexes
Gene Ontology:
Molecular function: double-stranded DNA binding; four-way junction DNA binding; phosphoprotein binding; protein binding; protein-macromolecule adaptor activity; R-SMAD binding; transcription cis-regulatory region binding; Y-form DNA binding; chromatin binding; DNA binding; DNA-binding transcription activator activity; sequence-specific DNA binding
Biological process: DNA damage response; negative regulation of cell cycle; negative regulation of DNA-templated transcription; negative regulation of JNK cascade; negative regulation of osteoblast differentiation; negative regulation of transcription by RNA polymerase II; osteoblast development; positive regulation of transcription by RNA polymerase II; positive regulation of transforming growth factor beta receptor signaling pathway; response to gamma radiation; response to UV; T-helper 2 cell differentiation; transcription initiation-coupled chromatin remodeling; DNA repair; negative regulation of cell population proliferation; regulation of transcription by RNA polymerase II
Cellular component: chromatin; cleavage furrow; cytoplasm; cytosol; histone methyltransferase complex; MLL1 complex; MLL1/2 complex; nuclear matrix; nucleoplasm; nucleus; protein-containing complex; transcription repressor complex; chromosome, telomeric region; endoplasmic reticulum lumen
Genetic constraint (gnomAD): Loss-of-function variants: 7 observed, 63.87 expected, observed/expected ratio (o/e) 0.11, 90% interval 0.061 to 0.21. The upper end of that interval is the gene's LOEUF score, 0.21, which puts it in group 1 of 6, group 1 being the genes least tolerant of losing a copy. Missense variants: 492 observed, 821.79 expected, observed/expected ratio (o/e) 0.6, 90% interval 0.56 to 0.64. Synonymous variants: 346 observed, 356.15 expected, observed/expected ratio (o/e) 0.97, 90% interval 0.89 to 1.06.
Gene-disease validity (ClinGen):
ClinGen rates the evidence that MEN1 causes each of these diseases.
multiple endocrine neoplasia type 1 (autosomal dominant): Definitive. An autosomal dominant tumor predisposition syndrome caused by pathogenic variants in the MEN1 gene, characterized by an increased risk of tumors of the parathyroid glands, pituitary gland, and foregut neuroendocrine tumors (most commonly pancreatic islet cells).
Cancer hallmarks: suppression of growth (promotes); proliferative signalling (promotes); escaping programmed cell death (suppresses)
Homologues: Orthologues: chimpanzee MEN1 (99% identical), macaque MEN1 (99% identical), pig MEN1 (98% identical), guinea pig MEN1 (97% identical), rat Men1 (97% identical), mouse Men1 (96% identical), dog MEN1 (96% identical), zebrafish men1 (67% identical), tropical clawed frog men1 (63% identical), Drosophila melanogaster Mnn1 (44% identical).
Diseases named in the same sentence as MEN1 in open-access papers:
MEN1 is named in the same sentence as 358 diseases in open-access papers, as found by Europe PMC text mining. Sharing a sentence is not in itself a finding about the gene and the disease. The quoted sentences say what the papers report.
multiple endocrine neoplasia type 1 (230 papers, 2000 to 2026). "Multiple endocrine neoplasia type 1 (MEN1), or Wermer’s syndrome, is a rare autosomal dominant genetic disorder caused by MEN1 mutations, which rarely result in thymic tumors." (PMID 41736142, 2026). "Multiple endocrine neoplasia type 1 (MEN1) is a hereditary endocrine tumor syndrome caused by a germline mutation on chromosome 11q13 in the MEN1 tumor suppressor gene, encoding menin." (PMID 40581735, 2026). "Multiple endocrine neoplasia type 1 is a hereditary syndrome strongly associated with PanNETs and pituitary neuroendocrine tumors (PitNETs), caused by germline mutations in the MEN1 gene." (PMID 41568565, 2026). "Multiple endocrine neoplasia type 1 (MEN1) is a genetic syndrome caused by inactivating germline mutations in the gene MEN1, encoding a chromatin scaffolding protein." (PMID 39896942, 2025). "Multiple endocrine neoplasia type 1 (MEN1) syndrome is an autosomal dominant disorder caused by a germline pathogenic variant in the MEN1 tumor suppressor gene." (PMID 39826015, 2025). "GEP‐NETs can occur sporadically or as part of a hereditary syndrome, such as multiple endocrine neoplasia type 1 (MEN1), or Von Hippel–Lindau syndrome, which are caused by mutations in the specific genes MEN1 and VHL, respectively." (PMID 39579056, 2025). "TNETs are part of the broad clinical spectrum of multiple endocrine neoplasia type 1 (MEN1), a hereditary tumor syndrome caused by germline mutations in the MEN1 gene." (PMID 40563625, 2025). "Multiple endocrine neoplasia type 1 (MEN1) is caused by a heterozygous germline mutation of the MEN1 gene on chromosome 11q13." (PMID 40277511, 2025). "Multiple endocrine neoplasia type 1 (MEN1) is an autosomal dominant syndrome caused by pathogenic variants of the MEN1 gene, leading to the development of tumours of various endocrine glands, typically pituitary, pancreas, and parathyroid glands." (PMID 40364143, 2025). "Background and Clinical Significance: Multiple Endocrine Neoplasia type 1 (MEN1) is a rare autosomal dominant disorder caused by mutations in the MEN1 gene." (PMID 40807067, 2025). "Most cases are sporadic, with less than 3% associated with multiple endocrine neoplasia type 1 (MEN1)." (PMID 41403981, 2025). "Multiple endocrine neoplasia type 1 (MEN1) is an autosomal dominant disorder caused by MEN1 gene mutations, typically involving primary hyperparathyroidism (PHPT), pancreatic neuroendocrine tumors (PanNETs), and/or pituitary neuroendocrine tumors (PitNETs)." (PMID 41222883, 2025). "Multiple endocrine neoplasia type 1 (MEN1) is a rare disease caused by mutations in the oncosuppressor gene MEN1 and characterized by co-occurrence of tumors of the parathyroid gland, pancreas, and pituitary gland." (PMID 40421248, 2025). "On the other hand, multiple endocrine neoplasia type 1 (MEN1) is an autosomal dominant endocrine disorder caused by mutations in the MEN1 gene." (PMID 40149663, 2025). "Multiple endocrine neoplasia type 1 (MEN1) is caused by inactivating mutations of the tumor suppressor gene MEN1, which encodes the protein menin." (PMID 41541958, 2025). "Mutations in the MEN1 gene results in abnormal menin protein production, which leads to MEN1 syndrome, demonstrated by development of multiple NEN tumors." (PMID 38123518, 2024). "Nine (13%) patients were presented with a constitutional gene mutation: four multiple endocrine neoplasia of type 1 (MEN1) and five neurofiromatosis of type 1 (NF1)." (PMID 39001434, 2024). "Germline mutations in the MEN1 gene remain undetectable in a notable subset of patients—ranging from 10% to 30%—who exhibit clinical manifestations consistent with MEN1 syndrome." (PMID 39201946, 2024). "Individuals with MEN1 syndrome are born with a pathogenic germline variant of the MEN1 gene and are at increased risk of developing neuroendocrine tumors (NETs)." (PMID 39336822, 2024).
multiple endocrine neoplasia type 1 (continued). "Multiple endocrine neoplasia type 1 (MEN1) is a rare autosomal dominant hereditary syndrome caused by a germline mutation in the MEN1 gene and characterized by a predisposition to various endocrine and non-endocrine tumors." (PMID 39518523, 2024). "More than 1500 individual MEN1 mutations have been reported in patients with MEN1 syndrome, with the majority resulting in protein-truncating variants with no clear correlation between genotype and phenotype." (PMID 38038882, 2024). "The pG4_HGMD1 located at MEN1 exon 2 contained 18 germline mutations linked to susceptibility to multiple endocrine neoplasia type 1." (PMID 39341500, 2024). "Multiple endocrine neoplasia type 1 (MEN1) is a monogenic, dominantly inherited disorder with a prevalence of approx. 1:20,000, caused by pathogenic variants in the gene MEN1." (PMID 38256138, 2024). "Multiple endocrine neoplasia type 1 (MEN1) is a rare autosomal dominant syndrome caused by inactivating pathogenic variants in the tumor suppressor gene menin 1 on chromosome 11q13." (PMID 38510015, 2024). "Germline mutations of MEN1 gene result in MEN1 syndrome, a rare autosomal dominant predisposition to benign and malignant tumors." (PMID 38294658, 2024). "Multiple endocrine neoplasia type 1 (MEN1) is a hereditary endocrine syndrome caused by pathogenic variants in MEN1 tumor suppressor gene." (PMID 38294658, 2024). "Type 2 G-NETs are linked with multiple endocrine neoplasia type 1 (MEN1) and Zollinger–Ellison syndrome (ZES)." (PMID 38254841, 2024). "Multiple endocrine neoplasia type 1 (MEN1) is an autosomal dominant disorder caused by mutations in the tumor suppressor gene MEN1 and is characterized by parathyroid, pancreatic islet, and anterior pituitary tumors." (PMID 38586714, 2024). "Multiple Endocrine Neoplasia type 1 (MEN1) is an autosomal dominant disorder marked by pathogenic variants in the MEN1 tumor suppressor gene, leading to tumors in the parathyroid glands, pancreas, and pituitary." (PMID 39104820, 2024). "Multiple endocrine neoplasia type 1 (MEN1) syndrome (or Wermer’s syndrome) is caused by heterozygous loss-of-function mutations in the tumor suppressor gene MEN1." (PMID 39336996, 2024). "Firstly, diagnosis of MEN1 syndrome can be made if a patient has at least two primary endocrine tumors associated with MEN1." (PMID 39201946, 2024). "Multiple Endocrine Neoplasia type 1 is a rare genetic syndrome mainly caused by mutations of MEN1 gene and characterized by a combination of several endocrine and non-endocrine manifestations." (PMID 37484956, 2023). "Although most PanNETs occur as sporadic tumors, they can also arise in association with syndromes such as multiple endocrine neoplasia type 1 (MEN1) and von Hippel–Lindau (VHL)." (PMID 37623030, 2023). "This contrasts with findings in the sporadic counterparts to other tumors typical of the MEN1 syndrome, such as parathyroid adenomas and gastrinomas in which somatic MEN1 gene mutation is very common." (PMID 37409236, 2023). "The tumor suppressor gene MEN1 (Men1 in mice) encodes the nuclear protein menin whose inactivation causes the development of multiple endocrine neoplasia type 1 (MEN1)." (PMID 37395406, 2023). "Multiple endocrine neoplasia type 1 (MEN1) is a rare genetic disorder, resulting from MEN1 gene abnormalities, which causes tumors mainly in the endocrine glands." (PMID 37179722, 2023). "The needle biopsy specimen was submitted for next-generation sequencing, which revealed a MEN1 gene mutation, and after further examination, a diagnosis of multiple endocrine neoplasia type 1 was made." (PMID 36941083, 2023). "The majority of insulinoma cases are sporadic with only 5-10% of insulinomas being linked with genetic syndromes, of which Multiple Endocrine Neoplasia type 1 (MEN1) is the most common." (PMID 37152923, 2023).
multiple endocrine neoplasia type 1 (continued). "MEN1 mutations can inactivate or disrupt menin function and are leading to multiple endocrine neoplasia type 1, a rare heritable tumor syndrome." (PMID 35287658, 2022). "Within clusters, Multiple endocrine neoplasia type 1, Gene Expression of Parathyroid Tumors was strongly correlated with MEN1 Mutations." (PMID 35198447, 2022). "Loss‐of‐function mutations in the MEN1 tumor‐suppressor gene cause the multiple endocrine neoplasia type 1 syndrome." (PMID 35509630, 2022). "MEN1, a tumor suppressor gene, was first studied as a germinative mutation associated with multiple endocrine neoplasia type 1." (PMID 35628190, 2022). "Multiple endocrine neoplasia type 1 (MEN1) is an inherited autosomal dominant tumor-predisposing syndrome caused by inactivating mutations of the MEN1 gene, which is located on chromosome 11q13 and encodes the 610 amino acid protein menin." (PMID 35696052, 2022). "Multiple endocrine neoplasia type 1 (MEN1) syndrome resulting from germline heterozygous loss-of-function mutations in the tumor suppressor gene MEN1 is well-recognized." (PMID 35323929, 2022). "Menin 1(MEN1) is considered as a tumour suppressor associated with multiple endocrine neoplasia type 1 sydrome." (PMID 35481717, 2022). "Multiple endocrine neoplasia type 1 (MEN1) is a hereditary cancer syndrome caused by germline variants in the MEN1 gene located on chromosome 11q13." (PMID 35255927, 2022). "Detection of MEN1 gene variants helps to distinguish MEN1 syndrome from other solitary tumors, such as somatic loss of heterozygosity (LOH) on chromosome 11q13, which is observed in 5–50% of such non-hereditary common sporadic tumors." (PMID 35255927, 2022). "Insulinomas appear sporadically or can be related with multiple endocrine neoplasia type 1 (MEN1 syndrome: an autosomal dominant condition due to MEN1 gene inactivating mutations)." (PMID 35954419, 2022). "MEN1 is also known as Wermer syndrome, considering that an association of endocrine tumors with an autosomal dominant pattern of inheritance was first described by Wermer in 1954." (PMID 36428828, 2022). "In the Basic Research cluster, its hotspots focus on Multiple endocrine neoplasia type 1, Parafibromin Immunostainings of Parathyroid Tumors, MEN1 Mutations and Calcium-Sensing Receptor and Vitamin D Receptor." (PMID 35198447, 2022). "Multiple endocrine neoplasia type 1 (MEN1) is an inherited disease caused by mutations in the MEN1 gene encoding a nuclear protein menin." (PMID 35954231, 2022). "A possible genetic mechanism of angiofibromas, collagenomas, and lipomas of patients with MEN1 syndrome is represented by the loss of heterozygosity of the MEN1 gene." (PMID 36428828, 2022). "While germline MEN1 mutations are pathognomonic to the hereditary syndrome, multiple endocrine neoplasia type 1, most somatic MEN1 mutations in GEP-NETs are sporadic, and are thought to play an important role in tumorigenesis." (PMID 36230691, 2022). "Patients with the multiple endocrine neoplasia type 1 (MEN1) syndrome carry germline heterozygous loss-of-function mutations in the MEN1 gene which predisposes them to develop various endocrine and non-endocrine tumors." (PMID 34515662, 2021). "MEN1 encodes Menin, is a tumor suppressor gene and a causative gene of multiple endocrine neoplasia type 1 (MEN1)." (PMID 34440096, 2021). "Multiple endocrine neoplasia type 1 (MEN1) is an autosomal dominant syndrome related to a mutation of the MEN1 gene and is characterized by a lifetime risk of developing primary hyperparathyroidism, duodenopancreatic NENs and pituitary tumors." (PMID 34885063, 2021). "Many mouse models of human MEN1 syndrome or somatic Men1 loss associated with sporadic pNETs have been developed, and all result in insulinomas." (PMID 34680266, 2021).